INS (insulin)
Diseases named in the same sentence as INS in open-access papers (continued):
Sharing a sentence is not in itself a finding about the gene and the disease.
Insulin resistance (continued). "Several studies, mostly based on in vitro and animal models, indicate that dietary polyphenols, mainly flavonoids, positively modulate the insulin signalling pathway by attenuating hyperglycaemia and insulin resistance, reducing inflammatory adipokines, and modifying microRNA (miRNA) profiles." (PMID 26879600, 2016). "In addition, there was a significant increase in fasting plasma insulin levels in the WD cohort, which in turn resulted in insulin resistance as assessed by HOMA-IR." (PMID 27458385, 2016). "Although there are some investigations about the protective effects of dietary intake of inorganic nitrate on insulin response and endothelial function, few studies report the influences of a direct intake of nitrate-enriched vegetables on insulin resistance in mice." (PMID 27616738, 2016). "Furthermore, the glycemic control and insulin resistance were analyzed under metformin and/or insulin therapy." (PMID 27579154, 2016). "Metabolic diseases such as obesity and coronary disorders could be a consequence of insulin resistance, i.e. the inability of insulin to drive glucose into the skeletal muscle and other tissues as liver, which can be caused by excessive body fat deposition." (PMID 27875996, 2016). "Their importance in the control of insulin secretion is underscored not only by their insulinotropic properties in insulin-sensitive individuals but also by the impairment of their action in experimentally-induced insulin resistance and T2D." (PMID 27798656, 2016). "Similarly, the consumption of a high-AGE diet (24.6 mg CML/day, LC-MS analysis) for one month led to increased fasting insulin and insulin resistance (HOMA-IR), compared to a diet low in AGEs (10.7 mg CML/day), in overweight women." (PMID 27271662, 2016). "A recent review stated that while aggressive insulin therapy post-operatively can improve morbidity and mortality rates, similar results can be attained by using pre-operative nutrition strategies to minimize insulin resistance." (PMID 27802272, 2016). "Peripheral blockade of DR could therefore result in increased insulin release and sensitivity, thus promoting adipogenesis, weight gain, insulin resistance, and ultimately type 2 diabetes, adverse metabolic effects also described for neuroleptics." (PMID 26808524, 2016). "However, one trial showed that a high-egg diet reduced plasma insulin levels and insulin resistance." (PMID 26993632, 2016). "We speculate that peripheral and local insulin resistance might share the same insulin/IGF receptor signaling mechanism and thus inhibit the PI3K/Akt signaling pathway that regulates uterine cell metabolism and function." (PMID 27461373, 2016). "It has been suggested that this effect, favoring insulin secretion, might constitute an adaptive response of the intestine to counterbalance diet-induced insulin resistance." (PMID 27148273, 2016). "However, once insulin resistance had improved, appropriate insulin dosing appeared to be important to resolve glucotoxicity for recovery of β cell function." (PMID 27766967, 2016). "The sexual dimorphism in liver cancer may also be related to differences in insulin sensitivity where females are more protected from diet-induced insulin resistance than males." (PMID 26924712, 2016). "As both insulin resistance and IGF-1 are linked to increased cancer risk, it is conceivable that myo-Ins modulation of insulin activity may efficiently contribute to reducing cancer risk." (PMID 27795708, 2016). "Previous work has shown that in rodent models of diet-induced obesity, vascular insulin resistance (measured as decreased insulin-stimulated Akt and eNOS phosphorylation) is necessary and sufficient for, and thus precedes, the subsequent development of organ-specific and systemic insulin resistance." (PMID 27128347, 2016).
Insulin resistance (continued). "In this study, we established insulin resistance in rats by feeding a high-fat diet,which demonstrated higher body weight, serum insulin level, visceral fat, FFAs, visceralfat/body weight ratio, and skeletal muscle TG deposition, all of which weresignificantly attenuated by exercise intervention." (PMID 27143172, 2016). "Altered myocardial insulin signaling is a hallmark of DCM; however, the molecular mechanisms that have been proposed to contribute to the development of insulin resistance in DCM are not fully understood." (PMID 27148064, 2016). "Insulin resistance leads to compensatory increase of insulin secretion and β-cell hypertrophy." (PMID 28101517, 2016). "Insulin resistance promotes adjustments in insulin secretion to preserve blood glucose control." (PMID 27111219, 2016). "Hyperthyroid patients presented with significantly lower serum levels of high-density lipoprotein cholesterol, LDLC and leptin, as well as higher levels of fasting insulin, resistin, adiponectin and homeostasis model insulin resistance index (HOMA-IR) than control (p < 0.05)." (PMID 27193069, 2016). "Using different approaches to identify the genes associated with T2D, more than 30 genes have determined contributing to insulin resistance, most of which could affect insulin signaling pathway." (PMID 27602317, 2016). "It has been suggested that fasting blood insulin levels greater than 15 mU/L may be useful for evaluating insulin resistance." (PMID 27069678, 2016). "GSI-induced adipose insulin resistance could reflect cell-autonomous (adipocyte) Notch-dependent or –independent effects or a compensatory response to increased hepatic insulin sensitivity." (PMID 26909319, 2016). "GCs induce insulin resistance and also inhibit insulin secretion from pancreatic beta cells." (PMID 26901633, 2016). "Thus, our data demonstrated the protective effects of Akt against β cell dysfunction and insulin resistance, which was further supported by the fact that Akt inhibitor increased the insulin resistance by decreasing the quantity of insulin secreted." (PMID 27034691, 2016). "It would be interesting to further investigate whether RCR extract, salidroside, mangiferin and other herb-derived insulin sensitizers share the similar mechanisms to modulate CD36 in ameliorating insulin resistance." (PMID 27405506, 2016). "Taken together, these results suggest that chronic rapamycin treatment is associated with impaired insulin synthesis or secretion, but not with insulin resistance." (PMID 27471110, 2016). "To test brain insulin resistance, we measured cortical levels of glucose and insulin and analyzed the expression and activation of the insulin receptor (IR) and its downstream signaling molecules IR scaffold-1 (IRS1), protein kinase B (AKT) and mammalian target of rapamycin (mTOR)." (PMID 26858121, 2016). "We have recently showed that in PTs of the Otsuka Long Evans Tokushima Fatty (OLETF) rat, an animal model of insulin resistance, the stimulatory effect of insulin on sodium bicarbonate cotransporter (NBCe1) activity via the PI3K/Akt pathway was also totally intact." (PMID 27247938, 2016). "However, impaired insulin action in the liver leads to insulin resistance characterized by impairment in the ability of insulin to inhibit glucose output." (PMID 27095446, 2016). "They hypothesized that it is not merely an increased mass of adipose tissue that directly leads to attenuation of insulin action, but rather adipose tissue inflammation mediated by activated immune system in obese individuals that leads to insulin resistance." (PMID 26918023, 2016). "FXR−/− mice exhibit peripheral insulin resistance, reduced glucose disposal, and decreased adipose tissue and skeletal muscle insulin signaling, and, conversely, activation of FXR by the agonist GW4064 in insulin-resistant ob/ob mice reduced hyperinsulinemia and improved glucose tolerance." (PMID 27006824, 2016).
Insulin resistance (continued). "OGDM were heavier and more adipose and had a higher prevalence of overweight/obesity and higher fasting insulin and insulin resistance (HOMA-IR) than control children, even after controlling for age, sex, and socioeconomic status in multiple regression analyses." (PMID 25478935, 2015). "Although obesity is a risk factor for insulin resistance and type 2 diabetes, not all obese people are insulin resistant and individuals have varying levels of insulin resistance for the same level of obesity." (PMID 25904939, 2015). "The generally higher degree of insulin resistance in NAFLD may explain a compensatory excessive increase in insulin secretion during OGTT, which is typical for IGT and early or newly diagnosed patients with T2D." (PMID 25933030, 2015). "There were no changes in glucose (760.4 ± 166.5 vs. 770.0 ± 165.5 min·mmol/L) or insulin AUC (22.9 ± 12.5 vs. 22.2 ± 12.5 min·μmol/L), in hepatic insulin resistance (2.0 ± 1.6 vs. 2.0 ± 1.2) or in ISI 16.0 ± 24.3 vs. 14.5 ± 26.6) in the entire pooled study population (p > 0.05)." (PMID 26512691, 2015). "Findings in support of this hypothesis may indicate a benefit for E2 in the management and prevention of feline diabetes, a condition of insulin resistance and diminished insulin secretion." (PMID 26086714, 2015). "Finally vildagliptin seems to reduce insulin resistance demonstrated by both reduction in serum levels of insulin and glucagon." (PMID 26170902, 2015). "Failure of the β-cell to secrete adequate amounts of insulin to compensate for insulin resistance may contribute to the pathogenesis of type 2 diabetes." (PMID 25855974, 2015). "This indicated that C. caudatus might have a beneficial effect on insulin sensitivity and insulin resistance despite the short-term intervention period." (PMID 26713097, 2015). "Insulin levels, the HOMA-IR index, total IGF-1 levels and increased insulin resistance are positively associated with CIMT; simultaneously, insulin resistance in obese adolescents can impair changes in CIMT and can lead to the early development of atherosclerosis." (PMID 26666335, 2015). "Since insulin is an activator of LPL, it has been suggested that the diminution of LPL activity may be due to a relative insulin deficiency and/or insulin resistance." (PMID 25725623, 2015). "Genetically determined insulin resistance could result in impaired insulin-mediated growth of fetal muscle, and the continuation of this pattern of body composition would lead to less muscle mass later in life." (PMID 25874126, 2015). "As a consequence, functional activity of the brain insulin signaling system is attenuated, which negatively affects the central control of peripheral metabolism and thus enhances the severity of metabolic disorders and insulin resistance." (PMID 28031898, 2015). "Indeed, overweight and obesity have been recognized as predictors for insulin resistance through dysfunction of adipocytes, whereas physical activity has been known as an important factor for the improvement of insulin sensitivity." (PMID 26488726, 2015). "Thus, to further analyze the association of IL-10 with these parameters, a correlation analysis was performed between IL-10 and both insulin and insulin resistance." (PMID 25944984, 2015). "Furthermore, IL-10 improves insulin sensitivity and glucose transport, thereby having a protective role against obesity-induced insulin resistance." (PMID 25960614, 2015). "It is possible that the increased insulin levels and/or insulin resistance could be more important for other cognitive profiles than those assessed in our study." (PMID 25798199, 2015). "Serine phosphorylation of the IR may inhibit the insulin excessive serine phosphorylation which was attributed to the post-binding defect and insulin resistance observed in these women." (PMID 25866577, 2015). "Also, some biochemical parameters were examined, including fasting blood glucose, insulin levels and insulin resistance." (PMID 25999625, 2015).
Insulin resistance (continued). "Insulin resistance refers to reduced peripheral insulin sensitivity." (PMID 26084330, 2015). "As the hypothalamic melanocortin signaling has an important role in regulation of glucose metabolism and insulin sensitivity, the decrease of its activity leads to hyperphagia, metabolic disorders, insulin resistance, and eventually to severe obesity, MS and T2DM." (PMID 28031898, 2015). "Results indicate that cognitive deficits in SHRs are accompanied by both central and peripheral insulin dysfunction, thus allowing for the speculation that SHRs might additionally be considered as a model of insulin resistance-induced type of dementia." (PMID 26110057, 2015). "Clinically, insulin resistance may be manifested by glucose intolerance for years before the diagnosis of diabetes, due to the effort of the endocrine pancreas to increase insulin secretion to maintain normal glucose levels." (PMID 26023930, 2015). "In the repaglinide cohort, rs831571 was significantly associated with decreased HbA1c levels after 24 weeks of treatment, the homeostatic model assessment of insulin resistance and fasting insulin level after 48 weeks of treatment with repaglinide (P = 0.0096, 0235 and 0.0212, respectively)." (PMID 26024304, 2015). "Currently, type 2 diabetes mellitus (DM2), characterized by insulin resistance and/or abnormal insulin secretion, either of which may predominate, affects 7.6 million people in Brazil, 26 million in the United States and 347 million worldwide." (PMID 26500555, 2015). "Additionally, as offspring became young adults, we found slight increases in insulin resistance in F1OB versus F1Con males with only minor decreases in insulin release to i.v. glucose infusion during IVGTT." (PMID 25875659, 2015). "So it is surmised that ECD can reduce blood glucose through the promotion of insulin secretion and result in the improvement of the apoB saccharification, so as to improve the insulin resistance and reduce the secretion of VLDL and TG in liver, ultimately improving hyperlipidemia." (PMID 26504476, 2015). "During the development of T2D, insulin resistance could increase insulin secretion to maintain normoglycemia, which termed β-cell compensation." (PMID 26147439, 2015). "Possibly, at this young age, the increased insulin resistance as a result of these risk factors presumably is not yet present or is fully compensated for by increased insulin production, resulting in normal glucose and HbA1c levels." (PMID 25875773, 2015). "Given the essential function of IRS1 in insulin signaling and the association of IRS1 variants with T2D as well as fat% and BMI, this gene is likely to be involved in fat distribution, adipocyte biology and/or insulin resistance." (PMID 26363598, 2015). "Considering this finding, higher HbA1c levels may indicate insulin resistance, while elevated GA levels are likely to reflect decreased insulin secretion, resulting in postprandial glucose excursion." (PMID 26099223, 2015). "Insulin resistance and thus increased levels of circulating insulin have repercussions in the CNS." (PMID 26041981, 2015). "For these possible pivotal roles of ROS, MT overexpression might interfere with ROS signals, resulting in impaired insulin secretion and insulin resistance during growth and aging." (PMID 26335571, 2015). "T2DM is characterized by insulin resistance and impaired insulin secretion." (PMID 25944304, 2015). "In a cross-sectional analysis of 1,440 Japanese adults, higher coffee consumption was associated with decreased insulin resistance, but not with insulin secretion, as evaluated through the homeostatic model assessment." (PMID 25978631, 2015). "We suggest that the observed increasein GLP-1-positive cell density triggered by high fat consumption in humans and mice mightfavour insulin secretion and therefore constitute an adaptive response of the intestine tobalance diet-induced insulin resistance." (PMID 26157580, 2015).
Insulin resistance (continued). "Dietary insulin load and DII could be considered as independent dietary risk factors for development of insulin resistance." (PMID 27446819, 2015). "Furthermore, mice null for caveolin-3 and caveolin-1 display insulin resistance, glucose intolerance and decreased insulin-induced glucose uptake; re-expression of these proteins reverses these conditions." (PMID 25914646, 2015). "Carbohydrate consumption leading to insulin secretion may create a pro-inflammatory milieu, particularly in the setting of obesity where insulin resistance is common." (PMID 26393645, 2015). "We may therefore deduce that GIP mRNA reduction in the intestine exposed to systemic insulin resistance corroborates GIP signaling defects in insulin-resistant and T2D subjects." (PMID 26376914, 2015). "Similarly the altered metabolic phenotype we observed in the BTBR mice, potentially associated with Wfs1 expression modulation, have been corroborated in the past, with BTBR mice having increased insulin resistance and higher fasting insulin levels." (PMID 26635614, 2015). "Contrary to our hypothesis, low-aerobic capacity was associated with enhanced aortic endothelial function and NO-mediated reactivity to insulin, despite increased adiposity and evidence of whole body insulin resistance." (PMID 26197933, 2015). "The loss of the repressive effect of insulin on the expression of CYP2E1 could be a possible link between OSAS, insulin resistance, and NASH." (PMID 25873773, 2015). "Thus, the decrease in insulin resistance is key for stable and improved glucose control, while the reserve of islet cell mass after resection is sufficient for adequate insulin secretion and glucose control." (PMID 26248027, 2015). "In patients with T2D, sleep disorders are associated with a 23 % higher fasting glucose level, a 48 % increment in fasting insulin levels and a decreased insulin sensitivity as indicated by a 82 % increase in homeostatic model assessment of insulin resistance (HOMA-IR)." (PMID 26204994, 2015). "Moreover, this study demonstrated that gut microbe-derived EVs, enhanced by the HFD, induced insulin resistance in insulin-responsive organs, thereby impairing glucose metabolism." (PMID 26510393, 2015). "Increased adiponectin levels observed in patients with PCOS after metformin administration may be the result of reduced insulin resistance and insulin levels." (PMID 26473366, 2015). "This suggests that the defects particular to insulin signaling may explain peripheral insulin resistance." (PMID 26194188, 2015). "Since most NAFLD patients suffer from obesity and insulin resistance, treatment options aim at weight reduction, control of dyslipidemia and improving insulin sensitivity through lifestyle changes and pharmacological agents, such as metformin, statins, fibrates, and thiazolidinediones." (PMID 26067236, 2015). "Hence, next we tested the peripheral insulin resistance as the insulin-stimulated glucose incorporation into lipids (adipose tissue) and glycogen (skeletal muscle)." (PMID 26236746, 2015). "Importantly, high fat diet-induced insulin resistance also leads to decreased insulin signaling and a predicted decrease in DAT activity." (PMID 25805560, 2015). "Furthermore, Let-7 transgenic mice exhibit impaired glucose tolerance because of diminished glucose-induced insulin secretion, and anti-miR–induced silencing of Let-7 has been proven to improve blood glucose levels and insulin resistance in obese mice." (PMID 26377847, 2015). "Therefore, along with the disruption of beta cell mass, alpha cell involution, and reduced plasma insulin levels the GIT2KO mice also demonstrate significant insulin resistance." (PMID 26834700, 2015).